MUC1 (mucin 1, cell surface associated)
Diseases named in the same sentence as MUC1 in open-access papers (continued):
Sharing a sentence is not in itself a finding about the gene and the disease.
tumor (continued). "Although present study demonstrated that application of nanobodies against tandem repeats of MUC1 could be an effective way to suppress tumor growth, angiogenesis, invasion, and metastasis, a number of limitations exists in present study." (PMID 34694686, 2022). "MUC1 is a typical glycosylated tumor antigen expressed on the surface of cancer cells." (PMID 36499455, 2022). "Importantly, the antibodies induced by DDA/MPLA liposomes efficiently recognized and killed MUC1-positive tumor cells through complement-mediated cytotoxicity." (PMID 35186882, 2022). "The results showed that MUC1 has higher levels of expression in tumor compared to normal tissues." (PMID 35879749, 2022). "Furthermore, the MUC1-Vax vaccine exhibited a significant therapeutic anti-tumor effect, which significantly inhibited tumor growth by expressing a high MUC1+ and PD-L1+ level of LLC and Panc02 tumor cells, and prolonged the survival of cancer-bearing animals." (PMID 35891256, 2022). "The free MUC1-N subunit may neutralize most MUC1 therapeutic antibodies, which limits the amount of antibodies targeting MUC1 protein on the surface of tumor cells." (PMID 36572921, 2022). "We report a new observation of MUC1 expression in the stroma-facing surface of canine tumor cells." (PMID 33761962, 2021). "To study whether MUC1 regulates expansion and migration of MDSCs to the spleen of tumor bearing mice, we analyzed splenocytes from these mice for Gr1+CD11b+ MDSC level by flow cytometry." (PMID 34070449, 2021). "Besides, mucin 1 (MUC1), a tumor driver gene in our study, is a membrane-bound protein whose gene expression is highest in the respiratory, digestive, and reproductive systems, and plays a role in cell growth, differentiation, and cell signal transduction." (PMID 33889544, 2021). "Many studies have shown that MUC1 regulates tumor cell proliferation and metastasis." (PMID 34715880, 2021). "Thus, the anti-MUC1-CAR4 T cells showed effective anti-tumor responses against the MUC1-expressing CCA spheroids." (PMID 33737613, 2021). "Hence, combination therapy with EpCAM/CD3 BsAb and MUC-1/CD3 BsAb was expected to be a promising strategy to enhance the anti-tumor efficacy." (PMID 34522164, 2021). "Along with the trajectory, epithelial cell marker EPCAM and ductal marker KRT19 exhibited sustained high expression levels during PDAC progression, while genes previously reported to be involved in tumor progression, such as MUC1 and CEACAM6, gradually upregulated along with the transition." (PMID 34732701, 2021). "Acs3 has proposed that the expression of MUC1/EMA on the periphery of IMPC tumor cell clusters may contribute to tumor progression and lymphatic metastasis." (PMID 33893728, 2021). "The Mucin-family protein, MUC1, impacts on carcinogenesis and tumor invasion." (PMID 34386419, 2021). "As hypothesized, wild-type mice vaccinated with surv.VLP-SS-MUC1 showed delayed tumour growth and improved overall survival compared to mice vaccinated with VLPs delivering either survivin or MUC1 peptides alone." (PMID 34066318, 2021). "Other than REG family and dual oxidase genes, microarray analysis suggested that expression of CEACAM6 and CEACAM7, members of the carcinoembryonic antigen-related cell adhesion molecule family, and MUC1, which inhibits the anti-tumor immune response, was upregulated by more than twofold." (PMID 33483567, 2021). "Next, we asked whether defucosylation of these humanized anti-MUC1 antibodies show more potent anti-tumor responses." (PMID 34070311, 2021). "Taken together, our data indicate that MUC1 might regulate Wnt/β-catenin signaling pathways to exert their tumor-activating functions in ICC." (PMID 34729096, 2021). "However, MUC1 is still considered a possible targetable option to enhance the fight against tumor cells." (PMID 33670011, 2021).
tumor (continued). "Such altered glycosylation facilitates, e.g., MUC1, main carrier of mentioned antigens in endothelial cells, to function as a ligand for, e.g., cell adhesion molecules and seeding at distant sites that forms secondary tumours." (PMID 34681197, 2021). "Silencing MUC1 expression has decreased tumor migration via activation of the PI3K/AKT signaling." (PMID 33692796, 2021). "From our data, it becomes clear that the therapeutic targeting of MUC1 must be specific to the tumor form of MUC1 because targeting normal MUC1 may lead to increased MDSCs." (PMID 34070449, 2021). "Moreover, MUC1 establishes various auto-inductive loops with MDSCs in the tumor microenvironment, which recruit the MDSCs in the MAPK and PI3K/AKT pathways manner." (PMID 33692796, 2021). "Similarly, Fujii and colleague reported the stimulative roles of ALKBH2 on the MUC1, an anti-adhesion molecule, on tumor cell growth." (PMID 34150745, 2021). "CCR in pCAR control that could also bind MUC1 and ErbB dimers elicited intermediate cytotoxicity, tumor re-stimulation potential, and cytokine release." (PMID 35028604, 2021). "In the context of the complex molecular crosstalk within the BC microenvironment, a growing body of evidence is showing that polarisation of TAM also occurs via recognition of highly glycosylated membrane-bound proteins on tumour cells (e.g., MUC1 and CD24) by lectins on macrophages." (PMID 33671245, 2021). "CA6 is a tumor-related antigen and one sialoglycotope of MUC1." (PMID 33724757, 2021). "The mouse xenograft model proved that YBX1 and MUC1 affected tumor volume and weight in vivo." (PMID 34976785, 2021). "Binding of galectin-3 to TF on MUC1 of tumour cells induces MUC1 cell surface polarization and exposure of smaller cell surface adhesion molecules/ligands, leading to increase of tumour cell-endothelium adhesion and tumour cell–cell homotypic aggregation, two important steps in metastasis." (PMID 34223877, 2021). "The high expression of MUC1 was significantly associated with the level of CA19-9 (P < 0.05), AFP (P < 0.05), and more aggressive tumor phenotypes including larger tumor size (P < 0.05), presence of lymph node metastases (P <0.05), vascular infiltration (P < 0.05), and advanced TNM stage (P < 0.05)." (PMID 34729096, 2021). "In addition, 13/25 (52%) patients developed peripheral T cell responses to any of the three tested tumor-associated antigens (PSA, brachyury, MUC-1)." (PMID 34831389, 2021). "The produced antibodies could recognize both murine and human tumour cells overexpressing MUC1, promoting tumour cell death through complement-mediated cytotoxicity (CDC)." (PMID 34073106, 2021). "Thus, humanized anti-MUC1 antibodies bind to the FcγRIIIa receptor on human NK cells and can induce their activation, potentiating them to recognize and lyse MUC1-expressing tumor cells." (PMID 34070311, 2021). "siPLK1-IONPs were conjugated with myristolated polyarginine peptide (MPAP), a type of membrane translocation peptide that facilitated the transfer into the cytoplasm, and tumor-selective peptide under the glycosylated MUC1-specific peptide (EPPT1) that enhanced the tumor-specific delivery." (PMID 34062991, 2021). "Endocytosis inhibitors can thus promote the expression of tumor-associated MUC1 epitopes, but do not have beneficial effects on NK cell-mediated tumor elimination using anti-MUC1 antibodies." (PMID 34070311, 2021). "Overall, MUC1 affects a variety of tumor progression pathways." (PMID 34207342, 2021). "In addition, extensive O-glycosylation of MUC1 contributes to cell resistance to anoikis, increasing cell adhesion and modulating the tumor immunological microenvironment through engagement of the lectin Siglec-9 127,128." (PMID 33531990, 2021). "In preclinical studies, Tn-MUC1 chimeric antigen receptor (CAR) T cells could control tumor growth in pancreatic cancer as well as in leukemia xenograft models without showing reactivity against normal tissue cells." (PMID 34638920, 2021).
tumor (continued). "Additionally, to impart tumor-targeting properties to the hybrid platforms, the authors conjugated MUC-1 DNA aptamer to them via a thiolate–maleimide (aptamer–PEG) reaction." (PMID 34361819, 2021). "Siglec-9 was expressed on TAMs and has been shown to interact with MUC1 on tumor cells." (PMID 33670444, 2021). "As a result, controlling IGF-1R signaling pathways by antagonizing MUC1 could be a critical step during tumor development." (PMID 33836774, 2021). "Interestingly, galectin binding to polyLacNAc extensions of MUC1 O-glycans has been shown to prevent NK cell attack on tumor cells." (PMID 33916770, 2021). "Due to the highly variable structure of MUC1, clarifying the specific effect of various MUC1 subtypes on tumor cells may have greater clinical significance." (PMID 33531990, 2021). "In addition, hyperglycosylated MUC1 can inhibit its processing and presentation to T cells by DCs as tumor antigens, thus blocking anti-tumor immune responses." (PMID 34207342, 2021). "Furthermore, mucin 1 (MUC1) overexpression in tumor cells can suppress normal E-cadherin function and cell adhesion." (PMID 34376211, 2021). "The data show that, in future, specific targeting of tumor-associated MUC1 (tMUC1) without targeting the normal MUC1 on immune cells should be a preferred strategy to increase efficacy against tumors." (PMID 34070449, 2021). "Of those, in n = 165 cases tumor tissue was available for analysis of MUC1 expression." (PMID 34386419, 2021). "In our study, a comparison of tumor growth and final wet weight between WT and MUC1KO mice indicate that in the absence of MUC1, mice are more susceptible to tumor growth with both KCKO and C57MG cell lines." (PMID 34070449, 2021). "MUC1 expression in CC is tightly related to dedifferentiation and tumor aggressiveness." (PMID 34445380, 2021). "These in vivo data confirmed that YBX1 promoted tumor growth by promoting MUC1 expression." (PMID 34976785, 2021). "It has been hypothesized that the MUC1 subunit harboring the TRs circulates at high levels among cancer patients and serves as a “sink” precluding the delivery of antibodies to the tumor cell surface." (PMID 33084221, 2020). "However, the tumor derived-organoids were positive for glandular markers MUC1 and SOX17, which confirmed their glandular origin." (PMID 32552764, 2020). "BALB/c mice were immunized with either ox- or red- M-FP then challenged with MUC1+ 3T3 tumor cells." (PMID 32351942, 2020). "Although activation of MUC1-mediated signaling in an autocrine/paracrine manner caused by ligation of LGALS3 promotes uncontrolled tumor cell malignancy, no role on hormone production/secretion has been described yet for this protein." (PMID 33066652, 2020). "The expression of MUC1 on the apical surface of normal glandular epithelial cells may reduce tumor-to-background contrast, thus, limiting the application of MUC1-targeting contrast agents." (PMID 33371487, 2020). "Evidences showed that MUC1 may act as an oncogene related to tumor formation and progression in many cancers." (PMID 33106534, 2020). "In addition, our data showed that with the activation of PI3K/Akt, proliferation and migration of tumor cells were also largely enhanced following MUC1 overexpression." (PMID 33375426, 2020). "AR20.5 forms a complex with circulating MUC1 and/or transmembrane MUC1 on tumor cells." (PMID 33167508, 2020). "More recently, a therapeutic regimen of AR20.5 in combination with anti-programmed death-ligand (anti-PD-L1) and polyinosinic-polycytidylic acid (PolyICLC) was explored in mouse models of pancreatic cancer and was found to produce MUC1-specific immune responses that suppress tumor growth." (PMID 32429033, 2020). "Recently, a study revealed significantly higher expression of the MUC1 protein in tumor cells than in normal cells through a specific cell ELISA technology, indicating that MUC1 may play an important role in carcinogenesis." (PMID 32777176, 2020).
tumor (continued). "The tumor markers MUC1 and MUC16 were identified as glycoproteins carrying the Tn cluster." (PMID 33019700, 2020). "MUC1-sialylated O-linked glycans on tumour cells binding to Siglec9 did not recruit SHP-1 or SHP-2 but induced calcium flux that lead to the activation of MEK-ERK kinases." (PMID 32322597, 2020). "Patients were categorized by tumor cell expression intensity low MUC1 vs. high MUC1." (PMID 31941061, 2020). "Furthermore, MUC1 in tumor cells has been shown to be aberrantly glycosylated, which results in overexpression of several novel tumor-associated carbohydrate structures that can serve as a possible prognostic marker or therapeutic target." (PMID 31941061, 2020). "Moreover, the serum levels of CA15-3 (MUC-1), which is a mucinous glycoprotein, is another commonly used tumor marker for preclinical detection of tumour recurrence and metastasis, in addition to patients’ follow up10." (PMID 32747636, 2020). "In contrast, overexpression of MUC1 would lead to increased anti-apoptotic activity of tumor cells." (PMID 33375426, 2020). "In addition, overexpression of MUC1 in CIPp-MUC1 cells inhibited the suppressing activity of disulfiram on the growth and metastasis of tumor cells, as well as inhibiting the pro-apoptotic effect of disulfiram." (PMID 33375426, 2020). "However, MUC1 is abnormally overexpressed and incompletely glycosylated in tumor cells, making it an ideal target for tumor immunotherapy." (PMID 32823603, 2020). "Accumulating evidence supported the involvement of the oncogenic MUC1 in tumor metastasis." (PMID 32662743, 2020). "For example, the oxidative conjugation of mannan and MUC1 FP through imine linkers induced Th1 type immune response and successfully protected mice from tumor growth, while reductive conjugation through amines induced Th2 type immune response without successful tumor protection." (PMID 32351942, 2020). "Additionally, compared with normal tissues, a similar downregulated expression of MUC1 was observed in the cardia tumor tissue (P = 3.51 × 10− 4)." (PMID 32122390, 2020). "MUC1 also serves as TAAs playing an important role in tumor immunotherapy." (PMID 32807223, 2020). "In addition, some tumor antigens derive their immunogenicity by means of aberrant post-translational modifications, as is the case for the MUC-1 glycoprotein where the tumor-restricted form is strongly hypo-glycosylated." (PMID 33679709, 2020). "Coupling of this nanobody to an anti-MUC-1 61 or an anti-CEA 193,194 nanobody was shown to mediate tumor growth inhibition when injected on a daily basis in mice receiving peripheral blood mononuclear cells and xenografted with MUC-1+ or CEA+ colon carcinoma tumors." (PMID 31695800, 2019). "MUC1 could be carried in extracellular microvesicles, which played a contradictory role in promoting both immunosuppression and tumor growth." (PMID 31739284, 2019). "Human MUC1/KL-6 in HCC patients was even described as a tumour marker." (PMID 30875782, 2019). "In addition, GGSK-1/30 exhibited much higher and more specific tumor enrichment levels than previously reported for other anti-MUC1 mAbs 32,33." (PMID 31588183, 2019). "In tumor cells, the glycoprotein MUC1 undergoes aberrant, truncated glycosylation." (PMID 30646616, 2019). "In addition, a considerable body of evidence suggests the sharing of some tumor antigens, such as hypoglycosylated MUC1, with other inflammatory diseases." (PMID 31131086, 2019). "Given that MUC-1 which is often expressed on tumor cells can also interact with ICAM-1, circulating cancer cells can adhere to endothelial cells which may represent the first step in metastases formation." (PMID 31231358, 2019). "In addition, a high level of MUC1 expression was associated with CRC in the rectum, deeper invasion, lymph node metastasis, distant metastasis, advanced tumor stage, and lymphatic invasion." (PMID 31933627, 2019).
tumor (continued). "Moreover, BBiApt recruited more CD16-positive immunocytes around MUC1-positive tumor cells and enhanced the immune cytotoxicity against the tumor cells in vitro." (PMID 30699986, 2019). "Since both SPN and MUC1 have been reported to limit T cell contacts with tumor cells in vitro, we hypothesized that tumor cells overexpressing these proteins may be less sensitive to T cell killing as a result of decreased clustering with T cells." (PMID 31882897, 2019). "Differential expression of MUC1 was observed only in malignant cases of both types of tumours." (PMID 30875782, 2019). "It remains to be examined whether MUC1 expressed by activated T cells leads to metabolic reprogramming of T cells as it does on tumor cells." (PMID 31468283, 2019). "MUC1 is an abundantly expressed transmembrane glycoprotein that undergoes several glyco-modifications during the process of malignant transformation, leading to the exposure of tumor-specific, novel carbohydrate epitopes." (PMID 30642093, 2019). "Here, we constructed a bispecific aptamer that could recruit CD16-positive immunocytes to MUC1-positive tumor cells and selectively enhanced the antitumor cytotoxicity." (PMID 30699986, 2019). "Rather, SPN and MUC1 modulate the degree of tumor cell sensitivity." (PMID 31882897, 2019). "The MUC1 protein is recognized as the second most targetable tumor antigen." (PMID 31178870, 2019). "Mucins may act as oncogenes and tumour-promoting (e.g., MUC1, MUC13), and/or tumour-suppressing factors (e.g., MUC15)." (PMID 30875782, 2019). "To select OECCL suitable for the production of cell lysates as the source of multiple tumor antigens, we first determined the expression levels of well-established OEC-associated antigens (CA-125, MUC1, ErbB-2, CEA, and survivin) in the CAOV3, SKOV-3, Hey, and A2780 cell lines by flow cytometry." (PMID 31886313, 2019). "MUC1 is a tumor marker that may serve as a potential target for treatment of a wide variety of cancers." (PMID 30699986, 2019). "On the other hand, mRNA expression of C7 and MUC1 was downregulated in squamous/basal-like tumours." (PMID 31439856, 2019). "Although BBiApt could recruit more CD16-positive cells around MUC1-positive tumor cells, it was still unknown whether these recruited immunocytes could enhance the cytotoxicity against the tumor cells." (PMID 30699986, 2019). "MUC-1 may protect tumor cells from immune surveillance by inhibiting antigen recognition by T cells, thereby, inhibiting the effector function of T cells and promoting an anti-inflammatory TME." (PMID 30987642, 2019). "Other MUC1 antibodies may be limited by their specificity, wherein they bind to tumor and normal MUC1." (PMID 31514488, 2019). "Importantly, under normal conditions, MUC1 is heavily glycosylated and expressed on the apical surface of epithelial cells, but in tumor cells MUC1 is aberrantly glycosylated." (PMID 30809507, 2019). "IHC staining of the MTag.MUC1 tumor sections confirmed high levels of MUC1protein expression." (PMID 31693710, 2019). "Additionally, some pairs of normal and tumour samples were probed for the luminal marker Muc-1 in parallel to Sox9, and the results were consistent with Sox9 being more highly expressed in tumour cells than in normal cells." (PMID 30622340, 2019). "CAR T cells against Tn-MUC1 effectively controlled tumor growth in murine xenograft models." (PMID 30483473, 2018). "Although expressed significantly on malignant cells, MUC1 targeting presents some complications as MUC1 is shed and may inhibit tumor antibody binding/recognition." (PMID 30031396, 2018). "The antigen processing ability of both X-DCs and S-DCs was evaluated employing two distinct formulations of the MUC1 tumor glycoantigen: a soluble recombinant MUC1 glycoprotein (rMUC1) and tumor-derived MVs carrying MUC1 (MVsMUC1), isolated from the MUC1 transfected DG75 cell line." (PMID 30455687, 2018).